KYNU (kynureninase)
Diseases named in the same sentence as KYNU in open-access papers (continued):
Sharing a sentence is not in itself a finding about the gene and the disease.
tumor (29 papers, 2019 to 2026). "The expression of KYNU was positively correlated with the expressions of ER (P = .002), PR (P = .007) and E‐cad (P = .03), while negatively associated with tumour grade (P = .008), tumour stage (P < .001) and the expressions of HER2 (P = .04) and Ki‐67 (P = .019)." (PMID 31332944, 2019). "Specifically, through differential gene expression analysis, we unambiguously identified the upregulation of the KYNU gene, a key player in tryptophan catabolism and the KP, as a pivotal regulator in supporting tumor growth." (PMID 40056038, 2025). "The expression levels of SMS, ASNS, PLOD2, P4HA1, PAH, and KYNU were upregulated in tumor samples compared with normal samples, and the remaining three genes were downregulated." (PMID 37511510, 2023). "Our data indicate that, besides CD73, GALC transduction induces an increase in the levels of the importin karyopherin subunit alpha 4, kynureninase, and RNA-binding motif protein 12, all involved in tumor immune escape." (PMID 37445731, 2023). "Treatment of tumors in vivo with an enhanced kynureninase to degrade kynurenine increased infiltration and proliferation of cytotoxic CD8s, resulting in improved tumor control in a variety of tumor types." (PMID 36479131, 2022). "Here the authors report the design of a hydrogel loaded with doxorubicin and Kyn-degrading kynureninase to relieve immunosuppression, showing anti-tumor responses in preclinical models." (PMID 35780226, 2022). "Here, we present a local chemo-immunometabolic therapy through injection of a supramolecular hydrogel concurrently releasing doxorubicin that induces immunogenic tumor cell death and kynureninase that disrupts Kyn-mediated immunosuppressive pathways in TME." (PMID 35780226, 2022). "It has been demonstrated that in tumor-bearing immune competent mice, administration of pharmacologically optimized PEGylated kynureninase (PEG-KYNase) promoted anti-cancer effects via increases in tumor infiltration and expansion of CD8+ lymphocytes." (PMID 35626147, 2022). "In summary, ADAR1 is recurrently associated with tumor-promoting functions across multiple cancer types—via editing of oncogenes (AZIN1, GM2A), suppression of innate immune signaling (PKR/MDA5), and stabilization of key proteins (KYNU)." (PMID 40852728, 2025). "The current study shows that GPX4 in tumor cells regulates the ubiquitination and expression of the lesser-studied enzyme KYNU in the kynurenine pathway by controlling intracellular ROS levels, affecting kynurenine levels in the TME and ultimately affecting macrophage polarization." (PMID 40365295, 2025). "Kynureninase (KYNU) is a potential prognostic marker for various tumor types." (PMID 37954130, 2023). "Additionally, KYNU is highly overexpressed, both in cell lines and tumor tissue of cutaneous squamous cell carcinoma (cSCC)." (PMID 36986469, 2023). "Kynureninase suppresses BC cell proliferation, tumour growth and development." (PMID 31332944, 2019). "Notably, its interaction with the metabolic enzyme KYNU unveils a novel immunometabolic axis that may facilitate immune evasion and support survival within an immune-cold tumor microenvironment." (PMID 40852728, 2025). "KYNU is a key enzyme in the kynurenine pathway of tryptophan metabolism, catalyzing the conversion of 3-hydroxykynurenine to 3-hydroxyanthranilic acid—a metabolic route increasingly recognized for its role in immune regulation, redox balance, and tumor immune evasion." (PMID 40852728, 2025). "Additionally, increased kynureninase activity may support tumor growth by enhancing de novo synthesis of nicotinamide adenine dinucleotide (NAD), a critical cofactor in bioenergetics and redox homeostasis." (PMID 40427178, 2025). "It is shown that CLEC7A, VCAN, and KYNU were significantly upregulated in monocytes, BIRC3 and SOD1 were mainly distributed in T cells, CCL20 was highly expressed in tumor cells, and CD69 was highly expressed in B cells." (PMID 35480896, 2022).
tumor (continued). "PEGylated Kynureninase (KYNU) combined with immune checkpoint inhibitors or cancer vaccine reduced Kyn levels in the TME, attenuated immune suppression and promoted tumour control in vivo." (PMID 34053179, 2021). "However, the roles of the tumor microenvironment (TME) and Kynureninase (KYNU) in LUAD remain largely unclear." (PMID 42284315, 2026). "These dual impacts—on RNS generation and NAD metabolism—highlight kynureninase’s potential as a critical regulator of immune evasion in LUAD and underscore the therapeutic promise of targeting KYNU to restore immune function in the tumor microenvironment." (PMID 40427178, 2025). "Furthermore, several other marker genes that are known to support tumor growth and creating an immune suppressive environment like IL6, IL10, C1QA, interleukin‐1 receptor antagonist (IL1RN), and KYNU were highly expressed in our Tri culture condition." (PMID 40056038, 2025). "When considering TCGA data, KYNU expression was significantly increased in LGG and GBM compared to control tissue; however, the expression of this enzyme significantly differed between GBM and LGG, being higher in the most aggressive tumor." (PMID 36986469, 2023). "Similarly, unique dose of recombinant kynureninase decreased Kyn levels and promoted higher levels of CD8 T cells in mice tumor models, thus modulating the effects of IDO1 and TDO2 within the TME." (PMID 35173722, 2022).
cancer (24 papers, 2016 to 2026). A tumor composed of atypical neoplastic, often pleomorphic cells that invade other tissues. "KYNU overexpression has been linked to the development and prognosis of several cancers." (PMID 39735553, 2024). "Conversely, KYNU-high tumors exhibit cancer cell-intrinsic expression and a depleted immune microenvironment, highlighting kynureninase’s dual role as a marker for stratifying immune contexts in LUAD." (PMID 40427178, 2025). "KYNU is an intermediate enzyme in tryptophan metabolism, and evidence suggests that plays an important role in cancer." (PMID 40616124, 2025). "KAT I and KYNU are however up-regulated in 9 and 5 cancer types, respectively, but are co-expressed with KMO in only 1 or 2 cancer types." (PMID 36286592, 2022). "By linking tryptophan catabolism to de novo NAD synthesis, kynureninase may help reconcile opposing metabolic pressures, ensuring cancer cell survival under conditions of redox and bioenergetic stress." (PMID 40427178, 2025). "A pharmacologically optimized human kynureninase is currently moving toward clinical development for the treatment of cancers where Trp-Kyn-AhR pathway play a significant immunosuppressive role through Kyn production, and those independently of both IDO1 and TDO2 overexpression." (PMID 35173722, 2022). "Indeed, some cancers such as HER2-positive and triple-negative mammary carcinomas overexpress the enzymes kynurenine 3-monooxygenase (KMO) and kynureninase (KYNU), causing increased production of anthranilic acid." (PMID 34517343, 2021). "Our finding of a lower Kyn/Trp ratio in BC concomitant to lower Kyn and Trp levels in plasma suggests a major decrease in Kyn vs. Trp in the presence of cancer, probably due to the hyperactivation of other downstream enzymes, such as kynureninase (KYNU) and kynurenine hydroxylase." (PMID 31337401, 2019). "has uncovered a novel functional axis involving ADAR1 and kynureninase (KYNU) in TNBC, highlighting a previously underappreciated editing-independent role for ADAR1 in cancer progression." (PMID 40852728, 2025). "AURKB, HOXB7, KYNU, and LCP1 are strongly upregulated in CESC, with the first two also upregulated in multiple other cancer types." (PMID 30918060, 2019). "To validate whether these enzymes regulate 3‐HA mediated ferroptosis, we first examined the expression levels of KYNU and HAAO in a panel of cancer cell lines." (PMID 36627132, 2023).
infection (1 paper, 2016). The state of being infected such as from the introduction of a foreign agent such as serum, vaccine, antigenic substance or organism. "Paralleling trends in the CNS of these animals, we found that upstream enzymes (IDO1, KMO, and KYNU) displayed significant mRNA upregulation during at least one phase of infection, while downstream enzymes (HAAO and QPRT) were either downregulated or unchanged." (PMID 28066416, 2016).
malformation syndrome (1 paper, 2021). "The authors described pathogenic variants in the KYNU and HAAO gene to be causative for this malformation syndrome (VCRL1, OMIM # 617660 and VCRL2, OMIM # 617661)." (PMID 34200361, 2021).
metabolic disease (1 paper, 2019). A congenital disorder (due to inherited enzyme abnormality) or acquired (due to failure of a metabolically important organ) disorder resulting from an abnormal metabolic process. "Kynureninase was associated with tryptophan utilization and metabolic diseases." (PMID 31332944, 2019).
neurodegenerative disease (1 paper, 2025). A disorder of the central nervous system characterized by gradual and progressive loss of neural tissue and neurologic function. "The KYNU inhibitors CBP and benserazide are commonly used in the treatment of neurodegenerative diseases; however, their potential for treating RIII remains unclear." (PMID 41017917, 2025).
KYNU also shares sentences with these, for which no sentence is quoted: depression (4 papers); cardiovascular disease (2); AIDS dementia complex (1); allergic disease (1); Alzheimer disease (1); amyotrophic lateral sclerosis (1); bipolar depression (1); cervical squamous cell carcinoma (1); cholestasis (1); cryptorchidism (1); diffuse large B-cell lymphoma (1); Dyskinesia (1); endocervical adenocarcinoma (1); esophageal carcinoma (1); head and neck squamous cell carcinoma (1); Huntington disease (1); hypospadias (1); injury (1); liver dysfunction (1); lung carcinoma (1); lymphoid neoplasm (1); malaria (1); metastatic cancers (1); neuroblastoma (1); omphalocele (1); osteoarthritis (1); ovarian serous cystadenocarcinoma (1); pancreatic adenocarcinoma (1); pancreatic cancer (1); periodontitis (1).
A further 6 diseases each share a sentence with KYNU in 1 paper.